CD4 (CD4 molecule)
Diseases named in the same sentence as CD4 in open-access papers (continued):
Sharing a sentence is not in itself a finding about the gene and the disease.
fungal infections (146 papers, 2009 to 2026). "Opportunistic fungal infections are more directly associated with cellular immune dysfunction—especially CD4+ T-cell counts below 200 cells/μL—than with viral load itself." (PMID 40943696, 2025). "Conversely, fungal infection progression is associated with a shift from Th1-type responses to Th2-mediated responses, characterized by CD4+ T-helper cells producing cytokines like IL-4, IL-5, and IL-10." (PMID 40005503, 2025). "We have previously shown that experimental fungal vaccine induced Tc17 cells are long-lived, stable without undergoing plasticity, and mediate vaccine immunity against fungal infections during CD4+ T cell deficiency." (PMID 40453072, 2025). "Monitoring CD4+ T-cell counts remains a critical tool for identifying individuals at elevated risk for opportunistic fungal infections and for determining the need for prophylactic or preemptive antifungal therapy." (PMID 40943696, 2025). "The global threat of fungal infections is alarming, especially in immunocompromised individuals with dysfunctional or deficient CD4+ T cells." (PMID 40491915, 2025). "B.Patients with a CD4 count of >500 cells/uL are susceptible to invasive fungal infections – Incorrect." (PMID 38304100, 2024). "IL-17 production is the hallmark of CD4+ T helper 17 cells (Th17), which play a crucial role in mucosal immunity against fungal infections and can be induced by C. albicans in vitro." (PMID 38134621, 2023). "Immunosenescence also contributes to the risk of fungal infection, due the reduction in naïve CD4+ and CD8+ T cells as well as decreased CD28 expression, which lead to a difficulty to recognise intracellular pathogens." (PMID 36946852, 2023). "CD4+ T cells, also called helper T cells, are instrumental in controlling fungal infections, and their deficiency leads to severe disseminated infections by opportunistic fungal pathogens." (PMID 36177012, 2022). "Most fungal infections are caused by opportunistic fungal pathogens under compromised CD4+ T cells or their functions." (PMID 36177012, 2022). "Previous study has showed that fungal infections were associated with impaired cell-mediated immunity and CD4+ T-cell responses were critical for protection against invasive fungal infections (IFIs)." (PMID 34025635, 2021). "Both SOT and HSCT share the polarization of CD4+ cells toward the Th2 phenotype that significantly correlates with the risk of contracting fungal infection." (PMID 34975811, 2021). "Immunocompromised individuals such as patients with HIV or decreased levels of CD4+ T cells are highly susceptible to S. aureus infections, and they are also at increased risk of developing fungal infections." (PMID 32817694, 2020). "Diminished number and/or function of white blood cells including CD4 count has long been realized as a major risk of fungal infection as well as difficult to control of disease." (PMID 28143591, 2017). "The risk of acquiring any opportunistic fungal infection increases with declining CD4 cell counts, especially when below a threshold of 200 × 106 l−1." (PMID 28080991, 2016). "CD4+ T cells are the primary effector cells that control fungal infections in healthy hosts, and their loss in lymphopenic patients necessitates targeting residual immune subsets to elicit antifungal immunity." (PMID 26367276, 2015). "In accordance to this notion, CD4+ T-cell-mediated responses have been observed in models of fungal infection where antibiotic use caused C. albicans overgrowth and increased levels of mast cells proliferation." (PMID 26192381, 2015). "When a patient's, CD4 count is below 200 cell/μL, there is an additional high risk of acquiring fungal infections such as Pneumocystis carinii pneumonia which bring a marked increase in mortality." (PMID 23181440, 2012). "These patients often have diminished or dysfunctional CD4+ T cells rendering them susceptible to fungal infections caused by Candida, Aspergillus, Cryptococcus, Histoplasma and Pneumocystis." (PMID 22829762, 2012).
fungal infections (continued). "We have previously shown that experimental attenuated live fungal vaccine-induced Tc17 cells are stable, long-lived without plasticity, and necessary to mediate sterilizing immunity during CD4+ T cell deficiency, which poses higher susceptibility to fungal infections." (PMID 40453072, 2025). "CD4+ T lymphocytes play an important protective role in patients with human immunodeficiency virus or acquired immunodeficiency syndrome who are susceptible to fungal infections such as Candida albicans, P. jirovecii, C. neoformans, and Aspergillus fumigatus." (PMID 36985244, 2023). "The CD4+ cells decimated lead to a decreased Th17 cytokine response and thus an increased susceptibility to fungal infections, which may negatively affect mortality." (PMID 37203184, 2023). "Moreover, patients infected with human immunodeficiency virus (HIV) become CD4+ T cell deficient over time, thereby making them prone to opportunistic bacterial and fungal infections." (PMID 35897089, 2022). "In addition, emerging evidence states that Th17 cells (another subtype of CD4+ TH cells) have also been implicated in the generation of specialized immune response against fungal infection and usually a balance between the Th1 and Th17 associated responses is desired." (PMID 36405591, 2022). "Similarly, IL-1R1, which has been shown to be essential for the induction of Th17 cells in different microbial or non-microbial models, was found here to be dispensable for inducing Tc17 and controlling fungal infection in vaccinated CD4+ T-cell deficient hosts." (PMID 22829762, 2012). "Most exhibit favorable initial responses to conventional PCM treatment when the mycosis is diagnosed at early stages, even though the majority present with low CD4 cell counts (<200 cells/μL)." (PMID 41494000, 2026). "CD4 + T cells that produce IFN-γ (T helper 1 [Th1] cells) chiefly mediate vaccine acquired resistance to fungal infections." (PMID 42079172, 2026). "Although the patient also had advanced HIV infection with a low CD4 count, his clinical features attributed to this invasive fungal infection were pronounced." (PMID 40861428, 2025). "The three independent prognostic factors (age, IgG level, and CD4+ T-cell count) were incorporated into a predictive model to estimate the probability of invasive fungal infection." (PMID 41081524, 2025). "In both fungal infections, the immune response includes a Th1 response mediated by CD4, CD8, and NK cells, with TNF-α secretion also by macrophages, neutrophils, and dendritic cells." (PMID 41156648, 2025). "Previous studies have shown that CD4+ T cells play a more prominent role in the later stages of fungal infections, with IL-17 production peaking after the initial fungal clearance." (PMID 39949778, 2025). "Consistent with our observations, most dermal CD4+ TRM cells in healed ear skin formed by fungal infection have been shown to persist in a scattered pattern while maintaining contact with APCs." (PMID 40791604, 2025). "CD4+ T cells and γδ T cells are recognized as the primary sources of IL-17 during fungal infections." (PMID 39949778, 2025). "Th1-associated cytokines, such as IL-1β, IL-2, IFN-γ, and TNF-α, play crucial roles in macrophage recruitment, activation, and the generation of reactive oxygen species to combat fungal infections while promoting CD4+ T-cell responses." (PMID 41425969, 2025). "In our model, we identified IFNγ (or) IL-17 secreting total CD4 + T cells and CD69 + activated CD4 + T cells that regulate fungal infection during C. auris reinfection." (PMID 40294061, 2025). "Immunity against fungal infections primarily relies on the activation of cellular immune responses, mediated by CD4+ T-helper cells." (PMID 40005503, 2025). "For example, a patient aged 70, with an IgG level of 5.5 g/L and a CD4+ T-cell count of 150/μL, would have a total score of 211 points, corresponding to an approximate 0.62 probability of invasive fungal infection." (PMID 41081524, 2025).
fungal infections (continued). "Previous studies have shown that various CD4+ T-cell phenotypes in the T-cell receptor (TCR) pathway play an important role in the host defense against fungal infection." (PMID 38172590, 2024). "The attributed reason is that fungal infection occurs mostly in immunocompromised hosts with low CD4 +T cell count, while studies rarely looked for vaccine development under immunodeficient conditions." (PMID 39440979, 2024). "IL-17A and F play crucial roles in the adaptive immune system’s response to fungal infections, which are generated by CD4 (specifically Th17) cells and stimulate epithelial cells to express antimicrobial peptides, as well as increase neutrophil trafficking." (PMID 38327523, 2024). "CD4+ T-cells activated by fungal products promote the long-term migration and activation of monocytes and macrophages, preventing invasive fungal infections." (PMID 37367619, 2023). "Interleukin-17 producing CD4+ helper T cells (i.e., Th17 cells) are pro-inflammatory immune cells that protect against bacterial and fungal infections." (PMID 36470166, 2023). "In summary, fungi infection enhanced glutaminolysis in CD4+ T cells to support the production of cytokines." (PMID 37124046, 2023). "T helper type 17 (Th17) cells, which are a subset of CD4+ T cells and are renowned for their ability to combat bacterial and fungal infections and mediate inflammatory responses, exhibit context-dependent effector functions." (PMID 37680632, 2023). "As expected, fungi infection significantly induced the up-regulation of OCR levels in human CD4 T cells." (PMID 37124046, 2023). "For example, in Irf4–/– mice, which exhibit impaired cDC2 migration, CD4 T cell responses to allergens and fungal infections in the intestine and lung were attenuated, consistent with a model showing that cDC2s prime CD4 T cells." (PMID 34480145, 2022). "CD4+ T cells are generally considered to play an important role in defense against fungal infections." (PMID 36439143, 2022). "The cytokines of MIP-1β, IL-8, and IL-16 played important roles in recruiting macrophages, neutrophils, and CD4 molecules, respectively, which are crucial immune cells against fungal infection." (PMID 35252030, 2022). "Infection with this virus is related to immune dysregulation, overexpression of pro-inflammatory cytokines, impaired cell-mediated immunity, and decreased CD4 and CD8+ T-cells that can increase the risk of invasive fungal infections." (PMID 35875562, 2022). "The CD4+ cell count for fungal infection ranged from 353-467 and was seen in stage 2 of the disease course." (PMID 34513432, 2021). "Peptide vaccines for human use must contain epitopes restricted to HLA-I and HLA-II to ensure the induction of a balanced and protective immune response against fungal infections involving CD4+ and CD8+ T lymphocytes." (PMID 34880863, 2021). "T-cells are known to play a vital role in the adaptive immune response against fungal infections, with both CD4+ and CD8+ cells known to be particularly vital in the host defense against Candida species." (PMID 34940403, 2021). "Adaptive immunity mediated by CD4+ T cells plays the major role in resolution of fungal infections, as evidenced by the high incidence of invasive fungal infections in patients with impaired CD4+ T-cell immunity." (PMID 34399628, 2021). "IL-17A is produced by a subset of CD4+ T cells, Th17 cells, which are part of the adaptive immune system and take a critical part in defense against extracellular bacterial and fungal infections." (PMID 34072201, 2021). "CD4+ T cells are generally considered to play a role in both the resolution and worsening of superficial or invasive fungal infections." (PMID 31813764, 2020). "T-helper-17 (Th17) cells are a subset of CD4+ T cells that can produce the cytokine interleukin (IL)-17 and play vital roles in protecting the host from bacterial and fungal infections, especially at the mucosal surface." (PMID 31824516, 2019).
fungal infections (continued). "DLI dose of 5 × 104/kg resulted in CD4 count > 100/μL by 120 days in 67% of patients and aGVHD II-IV in 11%; Fatal viral and fungal infections in 11%; 2 year OS: 69% for patients in remission at transplant." (PMID 31447852, 2019). "In this respect, CD4+ T helper cells play a critical role in protecting against fungal infection, and we previously have shown that Th1 and Th17 cells are required for NDV-3A vaccine-mediated protection against C. albicans." (PMID 31381597, 2019). "We used Tg1807 CD4+ T cells, which recognize the pan-fungal antigen calnexin and confer protective immunity against various fungal infections." (PMID 29782541, 2018). "It has been proposed that specific protection against a variety of mycoses corresponds to the activation of CD4+ T cells." (PMID 27799331, 2017). "In fungal infections, both CD4+ and CD8+ T cells participate in the elimination of fungal pathogens." (PMID 29358941, 2017). "The activity of CD4+ T cells against fungal infection in immunocompetent individuals has been very well characterized." (PMID 29358941, 2017). "In contrast, Ag-specific CD4+ T cells play the major role in fungal resistance, as evidenced by the high incidence of life-threatening fungal infections in patients with impaired CD4+ T cells." (PMID 28793349, 2017). "CD4+ T cells are the primary effector cells that control fungal infections in healthy hosts and Th17 cells are requisite for vaccination against the endemic mycoses of North America." (PMID 27542117, 2016). "Previous fungal infection increased CD4+ T-cell subset in spleen of EAE-mice (EAE+Ca group) and clearly upmodulated the production of many encephalitogenic cytokines by spleen cells stimulated with MOG or heat-killed C. albicans." (PMID 25969836, 2015). "Biopsy results demonstrated CD4 positivity, consistent with Mycosis Fungoides with coexpression of CD5, CD47, and CD7." (PMID 26380134, 2015). "Using Ag-loaded immunoliposomes to artificially reverse this defective migration, we show that recruited Ag-specific CD4+ T cells polarize toward a Th17 phenotype in the kidney and are protective during fungal infection." (PMID 25344471, 2014). "Conversely, superficial fungal infections, often observed in patients with higher CD4+ counts, may serve as early indicators of incomplete immune reconstitution or delayed HAART initiation." (PMID 40943696, 2025). "CD4+ T cell subsets play a pivotal role in the immune response to fungal infections." (PMID 40806563, 2025). "Recorded fungal infections were correlated with epidemiological variables and CD4+ T-cell counts." (PMID 40943696, 2025). "The delay in IFN-gamma response, prolonged hyperinflammatory state, and lower CD4 and CD8 cell numbers may exacerbate the cytokine storm and therefore increase the severity of COVID-19 infection and increase the risk of fungal infections too." (PMID 38690487, 2024). "CD4+ T cells (Th1, Th2, and Th17) secrete cytokines in response to fungal infections." (PMID 39267283, 2024). "Invasive fungal infections are common in patients with CD4 count of less than 200 cells/uL." (PMID 38304100, 2024). "Similarly, this study showed fungi infection enhances glutaminolysis in CD4+ T cells to support the production of pro-inflammatory cytokines, resulting in IBD progression." (PMID 37124046, 2023). "To investigate whether OXPHOS is involved in CD4+ T cell response under fungi infection, we detected OXPHOS levels in both fungi-infected and control humans as well as murine CD4 T cells by measuring OCR levels using seahorse analysis." (PMID 37124046, 2023). "Conversely, when co-induced with TGF-β and IL-6, CD4+ T cells differentiate into CD4+Th17 cells, a cell type known for secreting IL-6 and IL-17 while playing a significant role in defending against extracellular bacterial and fungal infections, inflammatory responses, and autoimmune reactions." (PMID 37941053, 2023).
fungal infections (continued). "Finally, we detected the glutamine metabolism enzymes GLS, GLS2, and GLUL mRNA expression under fungi infection in murine CD4+ T cells and CD4+ T cells obtained from CD and UC patients." (PMID 37124046, 2023). "This mycosis accounts for 15% of all causes of death in people with advanced HIV disease not receiving antiretroviral therapy (ART) and CD4 ≤ 100/μL in 2014, and for 19% mortality in those with CD4 < 200 cells/μL in 2020." (PMID 36547617, 2022). "HIV, which may be either HIV-1 or HIV-2, infects CD4+ T-lymphocytes and results in CD4 cells and a lowered immune system, which allows multiple bacterial and fungal infections." (PMID 36501281, 2022). "Severe COVID-19 disease is associated with an increase in pro-inflammatory markers, such as IL-1, IL-6, and tumor necrosis alpha, less CD4 interferon-gamma expression, and fewer CD4 and CD8 cells, which increase the susceptibility to bacterial and fungal infections." (PMID 34036149, 2021). "This may be explained by the fact that after engraftment, B-cell and CD4 T-cell recover slowly; however, HSCT patients are still at risk for viral and fungal infections as well as infections caused by encapsulated bacteria." (PMID 34970488, 2021). "In these patients, this is normally described as an increase in pro-inflammatory markers, such as IL-1, IL-6, and tumor necrosis alpha (TNF-α), less CD4 interferon-gamma expression, and a decreased number of CD4 and CD8 cells, which increase susceptibility to bacterial and fungal infections." (PMID 34575758, 2021). "CD4+ T lymphocytes are described as important protective cells in fungal infections." (PMID 28878763, 2017). "CD8+ Tc17 cells, like CD4+ Th17 cells, secrete IL-17A cytokines to activate epithelial cells (mucosal immunity) to secrete antimicrobial products such as defensin to fight against fungal infections." (PMID 29358941, 2017). "The course of the disease was characterized by CMV reactivation and severe and recurrent bacterial and fungal infections, which might be related to the decreased CD4 T cell count and the impaired functional capacities of neutrophils, respectively." (PMID 28243230, 2017). "Moreover, DCs isolated from the mLN of infected mice had a poor ability to co-stimulate CD4+ T-cells in vitro, indicating that Dectin-1 is involved in multiple complex pathways of DC activation in the GI tract during fungal infection." (PMID 26349660, 2016). "Assuming that CD4 counts of the 22 million untreated HIV-infected people are distributed uniformly, then about 2 988 000 are at increased risk of acquiring a life-threatening fungal infection." (PMID 28080991, 2016). "We also observed a depletion of Th22 cells in FIII, a subset of mucosal CD4+T cells that provides innate immune protection against bacterial and fungal infections and promote inflammation and epithelial proliferation and repair by secretion of IL-22 and Th17 cells co-expressing IL-22." (PMID 25503054, 2014). "Idiopathic CD4+ Lymphocytopenia is considered rare and is rarely considered within the differential diagnosis for Fine Needle Aspirations of otherwise healthy individuals with atypical fungal infections who present with mass lesions." (PMID 20806085, 2010). "However, the glutamine-free culture medium could reverse cytokine production by CD4+ T cells induced by fungi infection." (PMID 37124046, 2023). "However, the substantial loss of CD4+ T cells in HIV infection might lead to deficiencies in antifungal immunity, contributing to an increased risk of opportunistic fungal infections." (PMID 36439143, 2022). "These scenarios could ascribe to the possibility that NLRP3 inflammasomes instruct the trafficking and recruitment of effector CD4 T cells into the site of fungal infection (livers) while having a limited effect on CD4 T cell priming and differentiation in spleens in vivo." (PMID 34912336, 2021).